GTF2I (general transcription factor IIi)
Description:
Interacts with the basal transcription machinery by coordinating the formation of a multiprotein complex at the C-FOS promoter, and linking specific signal responsive activator complexes. Promotes the formation of stable high-order complexes of SRF and PHOX1 and interacts cooperatively with PHOX1 to promote serum-inducible transcription of a reporter gene deriven by the C-FOS serum response element (SRE). Acts as a coregulator for USF1 by binding independently two promoter elements, a pyrimidine-rich initiator (Inr) and an upstream E-box. Required for the formation of functional ARID3A DNA-binding complexes and for activation of immunoglobulin heavy-chain transcription upon B-lymphocyte activation.
Synonyms: GTFII-I; TFII-I; BAP-135; SPIN; BAP135; WBSCR6; BTKAP1; DIWS; IB291; WBS
Tractability: PROTAC: UniProt records ubiquitination sites on it; ubiquitination databases record sites on it; its protein half-life has been measured.
Gene: Protein-coding gene on chromosome 7 (74,650,231 to 74,760,706, forward strand). Ensembl gene ENSG00000263001.
Subcellular location: Cytoplasm; Nucleus
Subcellular location (Human Protein Atlas): Nucleoplasm
Gene Ontology:
Molecular function: DNA-binding transcription activator activity, RNA polymerase II-specific; protein binding; RNA polymerase II-specific DNA-binding transcription factor binding; DNA-binding transcription factor activity; DNA-binding transcription factor activity, RNA polymerase II-specific
Biological process: negative regulation of angiogenesis; positive regulation of transcription by RNA polymerase II; transcription by RNA polymerase II
Cellular component: membrane; nucleoplasm; nucleus; cytoplasm
Genetic constraint (gnomAD): Loss-of-function variants: 1 observed, 24.29 expected, observed/expected ratio (o/e) 0.0412, 90% interval 0.014 to 0.19. The upper end of that interval is the gene's LOEUF score, 0.19, which puts it in group 1 of 6, group 1 being the genes least tolerant of losing a copy. Missense variants: 75 observed, 235.31 expected, observed/expected ratio (o/e) 0.32, 90% interval 0.26 to 0.39. Synonymous variants: 65 observed, 83.92 expected, observed/expected ratio (o/e) 0.77, 90% interval 0.63 to 0.95.
Homologues: Orthologues: chimpanzee GTF2I (100% identical), pig GTF2I (98% identical), dog GTF2I (98% identical), guinea pig GTF2I (97% identical), mouse Gtf2i (97% identical), rabbit GTF2I (97% identical), macaque GTF2I (95% identical), rat Gtf2i (93% identical), tropical clawed frog gtf2i (66% identical). Paralogues in human: GTF2IRD2 (34% identical), GTF2IRD2B (34% identical), GTF2IRD1 (26% identical), ZMYM4 (8% identical), THAP12 (7% identical), ZMYM3 (7% identical), ZMYM6 (6% identical), ZMYM2 (6% identical), ZMYM1 (6% identical), ZBED11 (5% identical), ZBED8 (5% identical), EPM2AIP1 (5% identical), and 6 more.
Diseases named in the same sentence as GTF2I in open-access papers:
GTF2I is named in the same sentence as 93 diseases in open-access papers, as found by Europe PMC text mining. Sharing a sentence is not in itself a finding about the gene and the disease. The quoted sentences say what the papers report.
thymoma (47 papers, 2019 to 2026). A neoplasm arising from the epithelial cells of the thymus. "Recent genomic studies of thymic epithelial tumours have revealed that type A and AB thymomas are characterized by a high frequency of thymoma‐specific codon mutations (L424H) in the GTF2I gene." (PMID 41344988, 2026). "Mutations in GTF2I have been detected in up to 39% of thymic epithelial tumors (TETs), with a particularly high prevalence in type A thymomas (100%) and type AB thymomas (70%)." (PMID 41300989, 2025). "GTF2I is another transcription factor with a role in thymic development that is preferentially mutated in type A and AB thymomas." (PMID 38473304, 2024). "In our study, the pooled estimated mutation rate of GTF2I in thymomas was 0.4263 (95% CI [0.3590; 0.4936]), with minor heterogeneity, implicating the uniformity of the GTF2I mutation among the reported studies." (PMID 39272824, 2024). "The TCGA study has confirmed the notion that THs are among the adult tumors with the lowest mutational burden and very few recurrent gene mutations, with the notable exception of GTF2I mutations, which are preferentially found in type A and AB thymomas." (PMID 38473304, 2024). "There were 14 GTF2I mutations distributed according to histology: six in A thymomas, five in AB thymomas, two in B2 thymomas, and one in a thymoma with an unspecified subtype." (PMID 37671056, 2023). "Remarkably, the GTF2I mutation occurs at a single codon (L424H) and has been found in almost 100% of type A thymomas and in about 70% of type AB thymomas, while its prevalence decreases in more aggressive TETs, being found only in 8% of thymic carcinomas." (PMID 36836670, 2023). "GTF2I mutations, which are somatic and specific to thymomas, were used as an internal control to assess our ability to identify somatic mutations among germline alterations." (PMID 37671056, 2023). "GTF2I mutations are the most prevalent genetic alterations in thymomas which most commonly occur in type A and AB thymomas." (PMID 38067300, 2023). "Subtype 3 comprises type AB thymomas, with a high prevalence of GTF2I mutations and rich lymphocytic components." (PMID 36836670, 2023). "While somatic mutations are usually observed in thymic carcinomas, thymomas present only occasional mutations, with the exception of GTF2I, which is common in A and AB thymomas." (PMID 37671056, 2023). "For example, there is a high frequency of recurrent mutations in the GTF2I gene in type A and AB thymomas." (PMID 36916520, 2023). "Subtype 4 is constituted by type A and type B thymomas, with a high prevalence of GTF2I and HRAS somatic mutations." (PMID 36836670, 2023). "GTF2I mutation was the most common, present in 21% of the analyzed TETs, with 50% found in A thymomas and 38% in AB thymomas." (PMID 37671056, 2023). "Subtype 3 is characterized by type AB thymoma and is distinguished by a high prevalence of GTF2I mutations and abundant lymphocytic infiltration." (PMID 37849766, 2023). "Of note, all four patients harboring GTF2I mutations in the current study were diagnosed with thymoma, supporting GTF2I as a thymoma‐specific oncogene identified by previous studies." (PMID 36916520, 2023). "successfully engineered a murine model recapitulating the intricacies of GTF2I mutations, thereby successfully instigating thymoma formation in aged mice." (PMID 37849766, 2023). "According to TCGA data, human TETs with the GTF2I L424H mutation had an enrichment in cortical and intertypical thymic epithelial cell signatures compared with the GTF2I WT tumors, which mirrors thymomas in the Gtf2i mutated mouse model." (PMID 37671056, 2023). "Using PyClone analysis, the presence of GTF2I mutation was observed in up to 64% (14/22) of thymomas including in those with B histotype (43%; 6/14)." (PMID 37671056, 2023).
thymoma (continued). "On the contrary, in thymomas, GTF2I is an oncogene with recurrent mutations that are present in most of the A/AB thymomas and in a relevant number of B histotypes." (PMID 38201593, 2023). "There were 14 GTF2I mutations in 6 A, 5 AB, 2 B2 thymomas, and one in a thymoma with unspecified histology." (PMID 37671056, 2023). "Whereas human thymoma tissue rarely encompasses the entire thymus, so that mutant and normal parts co-exist within the same lobe, all TECs in transgenic mice carry the Gtf2i mutation." (PMID 36175547, 2022). "Researchers have found that there existed a high mutation rate of GTF2I in indolent thymomas, which was extremely rare in aggressive thymomas and thymic carcinomas." (PMID 35312867, 2022). "In contrast to thymomas, GTF2I mutation is only identified in 0 to 8% of thymic carcinomas, and has not been described in TNETs." (PMID 35198446, 2022). "Generally, a larger number of mutations, except in GTF2I, is present in thymic carcinomas compared to thymomas." (PMID 35884448, 2022). "Encouragingly, the phenotype of our transgenic mice resembles some aspects of human thymomas, indicating that mice are a suitable model species to assess the biology of thymomas associated with Gtf2i mutations." (PMID 36175547, 2022). "Through the analysis of thymoma mutation data from TCGA, we determined that GTF2I mutations were highly common in thymoma and were mostly missense mutations, which was consistent with previous findings." (PMID 36114454, 2022). "Thymic architecture and T cell repertoire analysis of a mouse model for thymoma and the role of the transcription factor GTF2I shows suitability of this model to recapitulate human thymomas and a severe effect of Gtf2i mutations on the medullary compartment." (PMID 36175547, 2022). "It is encoded by GTF2I, which has a high frequency of a missense mutation (chromosome 7 c.74146970T>A), particularly in type A thymomas (followed by type AB and type B thymomas)." (PMID 35884448, 2022). "With this objective in mind, we carried out a retrospective analysis, to assess the frequency of GTF2I mutation in Indian and German thymomas (mainly type A and AB) and to correlate it with clinical features." (PMID 34497477, 2021). "Out of a total of 89 type A/AB thymomas (including atypical forms), 71 (79.8%) were positive for the GTF2I mutation, including 78.6% (22/28) Indian and 80% (49/61) German cases." (PMID 34497477, 2021). "Third, since the total mutational burden of thymomas is extremely low, the prevalence of the only common and unique mutation, GTF2I, was the sole readout to study molecular differences between Indian and German thymoma patients." (PMID 34497477, 2021). "Previous studies also reported that GTF2I is the most frequently mutated gene in thymomas especially in type A and type AB TETs, however its frequency is lower than other types thymomas and thymic carcinomas." (PMID 34307137, 2021). "The GTF2I mutation was mainly enriched in subtype A and AB thymomas, consistent with the previous reports." (PMID 34568003, 2021).
thymoma (continued). "One of the most prevalent somatic mutations of thymomas is a single nucleotide hot-spot mutation (c.74146970T>A; p.L424H) in the general transcription factor IIi gene (GTF2I)." (PMID 33674910, 2021). "The Sanger results were consistent with the RNA-seq data, which further confirmed the occurrence of GTF2I mutation in thymoma samples." (PMID 34568003, 2021). "GTF2I is a thymoma-specific oncogene, and a high mutation frequency is seen in type A and AB thymomas." (PMID 34680386, 2021). "A leucine to histidine substitution (L383H, L404H) of GTF2I was recently identified to be one of the most frequent mutations in A and AB thymomas." (PMID 34568003, 2021). "In conclusion, the majority of thymomas harbor mutations in GTF2I that can be potentially used as a novel therapeutic target in patients with thymomas." (PMID 32722121, 2020). "Recent studies showed a missense mutation (chromosome 7 c.74146970T>A) in GTF2I (GTF: general transcription factor) present with high frequency in type A thymomas." (PMID 32722121, 2020). "We detected point mutations in GTF2I in all the type A and AB thymomas; several type B thymomas were also positive for these GTF2I mutations." (PMID 32722121, 2020). "In this study, we investigated the presence of point mutations in GTF2I in thymomas using targeted sequencing coupled with molecular barcoding to validate previous findings obtained by whole-exome sequencing." (PMID 32722121, 2020). "Type A thymomas possess a missense mutation in GTF2I (chromosome 7 c.74146970T>A) with high frequency." (PMID 32722121, 2020). "We also detected a GTF2I mutation for tumor 3154, reported as a micronodular thymoma with lymphoid stroma, a rare presentation of type A thymoma." (PMID 30897085, 2019). "Studies have suggested that patients with thymoma may display chromosomal instability and polygenic mutations, with a notably high mutation rate of the GTF2I gene in type A thymomas." (PMID 41497137, 2026). "Mutations in GTF2I are also common in thymomas, epithelial tumors of the thymus." (PMID 39864622, 2025). "GTF2I encodes a transcriptional factor with high mutation frequency observed in thymoma." (PMID 40523311, 2025). "In conclusion, based on a comprehensive review of the literature, we have developed a gene panel for targeted resequencing of thymic epithelial tumors and confirmed the presence of GTF2I mutations in a subgroup of thymomas among patients with myasthenia gravis." (PMID 37671056, 2023). "Therefore, it is not surprising that transgenic mouse models expressing mutated Gtf2i under the promoter of Foxn1 develop thymomas with cortical features instead of medullary features." (PMID 37671056, 2023). "Finally, Subtype 4 includes both type A and type AB thymomas and displays a relatively higher incidence of somatic mutations in GTF2I and HRAS." (PMID 37849766, 2023). "GTF2I mutations were exclusively detected in early-stage thymoma." (PMID 37627046, 2023). "GTF2I is an oncogene mutated in a subgroup of thymomas that is reputed to drive their growth." (PMID 37671056, 2023). "Clustering of thymoma samples using the genes associated with fatty acid metabolism divides the samples into two clusters largely overlapping the known histological types and differing in the prevalence of a recurrent GTF2I mutation." (PMID 35565274, 2022). "In The Cancer Genome Atlas study of 117 early-stage, resected thymic tumor specimens, molecular hallmarks of thymomas, which accounted for the majority of cases of this study, also included GTF2I mutations, specific for type A, and mutations in HRAS and NRAS mutations." (PMID 35749302, 2022). "Our analysis also shows frequent mutations of GTF2I in the TCGA THYM (thymoma) cohort." (PMID 35975235, 2022). "The GTF2I c.74146970 T > A mutation was detected in 82% of type A and 74% of type AB thymomas." (PMID 35975235, 2022). "GTF2I has a high mutation frequency (39%), particularly in type A and AB thymomas." (PMID 35884448, 2022).
thymoma (continued). "GTF2I mutation occurs at high frequency in thymoma and is a marker of good prognosis." (PMID 34104648, 2021). "Fourth, since the GTF2I mutation is largely restricted to type A and AB thymomas, the two patients cohorts were equally and strongly skewed towards an over-representation of these two histologies and are thus not representative regarding the histotype distribution." (PMID 34497477, 2021). "In addition, GTF2I, the gene with the highest frequency of mutations in thymoma, was missense mutation in all samples." (PMID 34104648, 2021). "A missense mutation in GTF2I was detected with high prevalence in and specific to thymomas." (PMID 32722121, 2020). "The common driver mutation in GTF2I was detected in ~64% of all thymomas; thus, molecular targeted therapy for GTF2I may be developed as the primary therapeutic strategy for patients with thymomas in the future." (PMID 32722121, 2020). "Mutations in GTF2I were detected in 14 out of 22 patients with thymomas (64%)." (PMID 32722121, 2020). "However, there are regional variations; studies in Japanese patients identified GTF2I mutations in all thymoma types except for Type B3, which may, in a few cases, show SMARCB1 and STK11 gene mutations." (PMID 38338833, 2024). "Thus, the mutation of GTF2I stood as a significant hallmark of type A and AB thymomas." (PMID 39272824, 2024). "Furthermore, the persistence of specific GTF2I mutations in certain subtypes could suggest a strong genetic link between them, which is exemplified in MN-T and Type A/AB thymomas." (PMID 38338833, 2024). "This therapeutic option could also be further pursued in thymoma patients with GTF2I mutations." (PMID 38473304, 2024). "Remarkably, a substantial fraction of thymoma lesions exhibited a conspicuous enrichment in gene signatures associated with cortical thymic epithelial cells (cTECs) and thymic epithelial progenitor cells (TEPCs), closely resembling the enrichment patterns observed in GTF2I-mutant human TETs." (PMID 37849766, 2023). "Thus, the present study is the first to address such differences through the comparison of Indian and German thymoma patients with regard to the prevalence of the thymoma-specific GTF2I mutation, clinical manifestation, paraneoplastic myasthenia gravis and histology." (PMID 34497477, 2021). "Thus, we focused on the importance of mutations in GTF2I in the development of type B thymomas using targeted sequencing coupled with techniques in molecular barcoding: more sensitive and specific assays than the whole-exome sequencing approach used in previous studies." (PMID 32722121, 2020). "In these studies, GTF2I mutation was accompanied with HRAS and NRAS mutations, suggesting a potential exclusivity to indolent thymomas." (PMID 38338833, 2024). "A GTF2I mutation has been found repeatedly in certain subtypes of thymoma and a GTF2I knock-in mouse model of thymoma has been successfully developed." (PMID 38730630, 2024). "Mechanistically, aberrant activation of cell cycle-associated pathways mediated by MYC and E2F signaling cascades likely serves as a crucial driving force behind the initiation and development of GTF2I-mutant thymomas." (PMID 37849766, 2023). "There are six known isoforms of GTF2I, but thymomas express only isoforms 2 (Beta) and 4 (Delta), according to RNA sequencing results." (PMID 37671056, 2023).